PRDX2 (peroxiredoxin 2)
Diseases named in the same sentence as PRDX2 in open-access papers (continued):
Sharing a sentence is not in itself a finding about the gene and the disease.
glaucoma (1 paper, 2023). Increased pressure in the eyeball due to obstruction of the outflow of aqueous humor. "In contrast, activation of the NRF2/ARE pathway by PLGA.EPO-R76E in glaucoma caused increased expression of Gpx 3, Prdx2, and Prdx6." (PMID 36978804, 2023).
glioblastoma (1 paper, 2023). The most malignant astrocytic tumor (WHO grade IV). "Here, we assessed the expression pattern of PRDX1 and PRDX2 in glioblastoma (GBM) and examined the efficacy of their inhibitors in GBM cell lines and patient-derived GBM cells." (PMID 37566013, 2023).
glioma (1 paper, 2012). A benign or malignant brain and spinal cord tumor that arises from glial cells (astrocytes, oligodendrocytes, ependymal cells). "Inhibition of catalase activity and decreasing PRDX2 expression sensitized glioma cells to oxidative stress and ionizing radiation, respectively." (PMID 22916164, 2012). "In support of this, previous studies have shown that antioxidant proteins catalase and PRDX2 are also highly expressed in glioma cells." (PMID 22916164, 2012).
Huntington disease (1 paper, 2021). Huntington disease (HD) is a rare neurodegenerative disorder of the central nervous system characterized by unwanted choreatic movements, behavioral and psychiatric disturbances and dementia. "PRDX2 was significantly increased in the frontal cortex of DS, AD, and PD patients, the hippocampus of AD patients, and the striatum of Huntington’s disease (HD) patients." (PMID 33810179, 2021).
Hydrocephalus (1 paper, 2024). Hydrocephalus is an active distension of the ventricular system of the brain resulting from inadequate passage of CSF from its point of production within the cerebral ventricles to its point of absorption into the systemic circulation. "First, recent studies have shown that in addition to iron, other degradation products of hemoglobin (e.g., peroxiredoxin 2) also contribute to the development of hydrocephalus after IVH." (PMID 37208490, 2024).
infertile (1 paper, 2019). "Of the four validated proteins, SPA17 and SERPINA5 were underexpressed and ANXA2 was overexpressed (p < 0.05) in UMI subjects, whereas the expression level of PRDX2 was comparable for normozoospermic fertile and infertile men." (PMID 31336797, 2019). "However, validation of PRDX2 using the Western blot technique revealed that the protein levels were comparable in both the normozoospermic fertile and normozoospermic infertile men." (PMID 31336797, 2019).
influenza (1 paper, 2015). An acute viral infection of the respiratory tract, occurring in isolated cases, in epidemics, or in pandemics; it is caused by serologically different strains of viruses (influenzaviruses) designated A, B, and C, has a 3-day incubation period, and usually lasts for 3 to 10 days. "Interestingly, the PRDX2 dimer runs as a doublet in influenza-infected cells, but as a single band in non-infected controls." (PMID 25985305, 2015).
insulinoma (1 paper, 2021). "Among the first to assess peroxiredoxin expression in β-cells were Bast and colleagues in 2002, who observed that PRDX1 and PRDX2 are expressed in the cytoplasm of INS-1 insulinoma cells and in islets of BalbC mice." (PMID 34557160, 2021). "There is controversy concerning the responsivity of peroxiredoxins to stress, as Zhao and Wang observed decreased protein expression of PRDX2 in MIN6 insulinoma cells in response to inflammatory cytokines (IL-1β, IFN-γ, and TNF-α) or STZ, rather than increased expression." (PMID 34557160, 2021).
intracerebral hemorrhage (1 paper, 2024). A cerebrovascular disorder characterized by bleeding into one or both cerebral hemispheres including the basal ganglia and the cerebral cortex. "Peroxiredoxin 2 (Prx2), an intracellular protein that regulates redox reactions, released from red blood cells is involved in inflammatory brain injury after intracerebral hemorrhage (ICH)." (PMID 38516845, 2024).
Jaundice (1 paper, 2022). Yellow pigmentation of the skin due to bilirubin, which in turn is the result of increased bilirubin concentration in the bloodstream. "In contrast to the membrane disruption of red blood cells and Heinz bodies formation in favism, G6PD deficiency causing jaundice is perhaps attributed to the disruption of oxidant-antioxidant balance, impaired recycling of peroxiredoxin 2, thus affecting bilirubin clearance." (PMID 35685917, 2022).
liver steatosis (1 paper, 2025). "We also observed a general improvement of hepatic metabolism, in particular on bile acid and fatty acid metabolism, in line with the decrease of liver steatosis observed in Prdx2-KO mice." (PMID 40932790, 2025). "Altogether, these data demonstrate that targeting PRDX2 in diseased livers improves liver steatosis and prevents HCC development, most likely independently from fibrosis." (PMID 40932790, 2025). "In contrast, we observed a decrease in liver steatosis and LDL cholesterol levels in Prdx2-KO animals, supporting a functional role for Prdx2 in lipid metabolism regulation." (PMID 40932790, 2025).
lymphedema (1 paper, 2021). Excess fluid collection in tissues, causing swelling. "Considering that hemoglobin may be easily influenced during venipuncture and that the focus of this study was to investigate the oxidative stress associated with lymphedema, we chose four other protein targets (CAT, PRDX2, CA1, and CA2) for further validation of their expression by ELISA." (PMID 33917571, 2021).
nasal polyps (1 paper, 2022). "We, thus, aimed to evaluate the transcriptional patterns of ADCAP1, BPIFA1, SOD, and PRDX2 genes across different locations of the nasal cavity, including nasal polyps, bulla ethmoidalis, and middle nasal turbinate tissue of CRSwNP patients." (PMID 35628331, 2022).
neuroblastoma (1 paper, 2023). Neuroblastoma (NB) is the most common solid, extracranial childhood tumor. "In an effort to identify whether overexpressed Prdx-2 has a protective effect and affects SIRT1 in PD, the human neuroblastoma cell line SH-SY5Y and transfection with Prdx-2 were used to investigate." (PMID 36808393, 2023).
pancreatic disease (1 paper, 2023). "Among these proteins, six (AAT, IGFBP2, RAB2B, PRDX2, RHOC, and LMNA) with functions closely related to pancreatic disease were selected for further validation." (PMID 36712921, 2023).
pancreatic ductal adenocarcinoma (1 paper, 2020). An infiltrating adenocarcinoma that arises from the epithelial cells of the pancreas. "Prdx2 expression was elevated and intracellular reactive oxygen species (ROS) levels were reduced in QGP-1 cells as compared with control pancreatic ductal adenocarcinoma (PDAC) cells (BXPC3 and CFPAC)." (PMID 33182509, 2020).
pancreatic neuroendocrine neoplasm (1 paper, 2020). A neoplasm with neuroendocrine differentiation that arises from the pancreas. "Prdx2 may suppress the growth of pancreatic neuroendocrine neoplasms and could be a marker for predicting the efficacy of mTOR inhibitors." (PMID 33182509, 2020).
preeclampsia (1 paper, 2019). Preeclampsia is a hypertensive disorder of pregnancy that is characterized by new-onset hypertension with proteinuria presenting after 20 weeks of gestation, and depending on mild or severe forms may initially present with severe headache, visual disturbances, and hyperreflexia. "Applying Proteomic technology, a 2D-PAGE and MALDI-TOFMS study showed that Prdx2 was down-regulated in placental trophoblasts from patients with preeclampsia." (PMID 31636515, 2019).
Pruritus (1 paper, 2024). Pruritus is an itch or a sensation that makes a person want to scratch. "For example, the antioxidant protein Prdx2 showed significant downregulation in all pruritus groups." (PMID 38577622, 2024).
pterygium (1 paper, 2021). A wedge-shaped fibrovascular lesion arising from the bulbar conjunctiva and extending to the cornea. "Some of these molecules are upregulated in pterygium samples, including ALDH3 and PRDX2." (PMID 34707671, 2021).
pulmonary hypertension (1 paper, 2017). Increased pressure within the pulmonary circulation due to lung or heart disorder. "The data presented in this article are related to the research paper entitled “peroxiredoxin-2 plays a pivotal role as multimodal cytoprotector in the early phase of pulmonary hypertension”." (PMID 29034295, 2017).
renal carcinoma (1 paper, 2023). A carcinoma arising from the epithelium of the renal parenchyma or the renal pelvis. "Consequently, whether VM exerts a favorable influence on renal cancer prognosis through alternative pathways or if PRDX2 affects ccRCC prognosis via mechanisms distinct from VM remains unclear." (PMID 38178861, 2023).
renal cell carcinoma (1 paper, 2018). "In addition, previous studies demonstrated that patients exhibiting PRDX2 positive had a better prognosis than their PRDX2 negative counterparts in renal cell carcinomas and astrocytic brain tumors." (PMID 30104402, 2018).
retinal detachment (1 paper, 2015). An eye emergency condition which may lead to blindness if left untreated. "Protein spots that were upregulated in the vitreous following retinal detachment were identified as albumin fragments, and those downregulated were found to be peroxiredoxin 2, collagen-Iα1 fragment, and α-1-antiproteinase F. Conclusions." (PMID 26664739, 2015). "Indeed, the present study showed a decrease in the vitreal levels of peroxiredoxin 2 following retinal detachment." (PMID 26664739, 2015). "Indeed, peroxiredoxin 2 and other members of this family of proteins are liable to have a significant role in the pathophysiology of retinal detachment." (PMID 26664739, 2015).
Sepsis (1 paper, 2017). Sepsis is defined as life-threatening organ dysfunction caused by a dysregulated host response to infection. "PRDX2 deficiency as well as PRDX3 deficiency were increased LPS-induced septic shock in mice, and circulating PRDX4 level was reported as oxidative stress marker in patient with sepsis." (PMID 28881633, 2017).
Sjögren’s syndrome (1 paper, 2024). "With further analysis, the levels of S100A8 and S100A9 were found to be upregulated in Sjögren’s syndrome patients with DED, whereas the levels of lactoferrin and peroxiredoxin 2 (Prx2) decreased." (PMID 38671870, 2024).
systemic vasculitis (1 paper, 2011). "Interestingly, PRDX2 has recently been identified as a target of anti-endothelial cell antibodies in systemic vasculitis." (PMID 21569507, 2011).
tuberculosis (1 paper, 2020). A chronic, recurrent infection caused by the bacterium Mycobacterium tuberculosis. "This signature also identified a novel gene in tuberculosis pathogenesis, PRDX2, a member of the reactive oxygen species scavenger system." (PMID 32967690, 2020). "Further studies are warranted to explore the role of PRDX2 in early infection, and how that response may be skewed by HIV and other known tuberculosis risk factors." (PMID 32967690, 2020).
vascular tumours (1 paper, 2023). "Experimental studies have revealed that PRDX2 exhibits higher expression in benign vascular tumours compared with malignant vascular tumours such as Kaposi’s sarcoma and angiosarcoma." (PMID 37758743, 2023).
cancer (80 papers, 2006 to 2026). A tumor composed of atypical neoplastic, often pleomorphic cells that invade other tissues. "Growing evidences indicate that there is a closely association between the PRDX2 expression and the progression of cancers." (PMID 32908916, 2020). "Recently, increasing attentions have been paid to the association with PRDX2 and the progression of cancers." (PMID 32908916, 2020). "Peroxiredoxin-2 (Prdx2), an antioxidant enzyme, plays an important role in the protection of cancer cells from oxidative radical damage caused by hydrogen dioxide (H2O2), which is a potential target for cancer therapy." (PMID 30988280, 2019). "The new probe reveals peroxide-induced oxidation in human cells below the detection limit of current probes, as well as peroxiredoxin-2 oxidation caused by two different redox cancer therapeutics in living cells." (PMID 30087344, 2018). "PRDX2 is associated with tumor progression and has been implicated in the metastasis of cancers through its interactions with TGFβ1-induced epithelial-mesenchymal transition." (PMID 28765537, 2017). "Take together, these findings suggest that PRDX2 is closely associated with the proliferation, metastasis, radio-resistance and drug-resistance of cancer." (PMID 28125800, 2017). "PRDX2 has also been implicated in promoting cancer development, progression, and metastasis." (PMID 39939411, 2025). "Moreover, Prdx3 and Prdx2 have been associated with cancer aggressiveness and patient survival, and higher Prdx2 and Prdx3 expressions were associated with less aggressiveness and longer survival." (PMID 33425206, 2020). "Moreover, it has also been reported that PRDX2 was associated with the maintenance of cancer stem cells (CSCs) in liver cancer." (PMID 32908916, 2020). "Our findings suggest that MDSCs or cancer cells in 4T1 tumors express Spp1, Ltf, Calr, and Prdx2, potentially influencing elevated plasma concentrations." (PMID 39939411, 2025). "Three (SPP1, CALR, and PRDX2) of the four enriched biomarkers in this study were found to be expressed mainly in cancer cells." (PMID 39939411, 2025). "The spleens of 67NR‐bearing mice showed the highest expression level of Prdx2, and the cancer cells of 4T1 at both early and late stages expressed similar levels of Prdx2." (PMID 39939411, 2025). "PRDX2 protein levels were higher in the peritumoral area where the cancer cells were exposed to abnormal extracellular matrix or immune cell infiltration, with a gradient from the periphery to the core of the tumor." (PMID 40932790, 2025). "Spp1, Calr, and Prdx2 were highly expressed in 4T1 cancer cells, whereas Ltf was highly expressed in MDSC within 4T1 tumors." (PMID 39939411, 2025). "Immune‐related proteins–osteopontin (Spp1), lactotransferrin (Ltf), calreticulin (Calr) and peroxiredoxin 2 (Prdx2)–were associated with systemic myeloid‐derived suppressor cell (MDSC) burden, highlighting their potential roles in malignant tumors." (PMID 39939411, 2025). "These markers were expressed in cancer cells or MDSC in the 4T1 model, and osteopontin and peroxiredoxin 2 were associated with low survival probability and high recurrence in patients with triple‐negative breast cancer." (PMID 39939411, 2025). "Of note, PRDX2 protein expression was also increased in cancer cells compared with isolated primary human hepatocytes (PHHs)." (PMID 40932790, 2025). "In contrast, PRDX2 KO in cancer cells induces mitochondrial and ER stress, leading to reduced cell proliferation and an increase in apoptosis upon oxidative stress in an AMPK-independent manner." (PMID 40932790, 2025). "To determine the primary cell populations expressing Spp1 (Spp1), Ltf (Ltf), Calr (Calr), and Prdx2 (Prdx2), we conducted qPCR analysis of whole spleen tissue, where MDSCs were mainly generated, MDSCs sorted from tumors, and cancer cells." (PMID 39939411, 2025).
cancer (continued). "Perturbation studies in HCC cell lines, a cell line–derived xenograft mouse model, and patient-derived HCC spheroids revealed that PRDX2 also mediates cancer initiation, cancer cell proliferation, and survival through its antioxidant activity." (PMID 40932790, 2025). "We observed a reduced number of colonies and tumor spheres in KO cells, indicating that PRDX2 KO impaired tumor initiation and self-renewal properties of cancer cells." (PMID 40932790, 2025). "Then, we rescued PRDX2 WT or C51S mutant expression in PRDX2-KO cancer cells and assessed cancer cell phenotype by performing clonogenic and tumor spheroid assays." (PMID 40932790, 2025). "Specifically, aberrations in PRDX2 potentially influences cellular proliferation and contributes to various carcinomas." (PMID 40128671, 2025). "On the basis of these results, PRDX2 has been recognized as a potential therapeutic target in cancer." (PMID 39234629, 2024). "The findings demonstrate that peroxiredoxin 6 is related to the cancer development and stress response while peroxiredoxin 2 is likely more relevant to stress response." (PMID 38249992, 2024). "High expression of PRDX2 has also been reported in various cancer cells and tissues, contributing to cancer progression." (PMID 38188679, 2023). "Here, LCP1, PRDX2, OGN and, TAGLN2 together with other molecular interactors, linked with highest hits, according to KEGG database, to pathways in cancer, PI3K-AKT and MAPK signaling pathways." (PMID 38322285, 2023). "Meanwhile, PRDX2 overexpression correlates with cancer progression in several malignancies, including colon, prostate, cervix, and lung." (PMID 38178861, 2023). "It has been shown that PRDX2 can suppress or enhance tumorigenesis depending on context, cells, and cancer type, etiology, and stage." (PMID 38178861, 2023). "In particular, circDIDO1 overexpression inhibited the expression and activity of β-catenin in GC cells, which is in accordance with previous studies showing that PRDX2 is an important regulator of β-catenin signaling pathway in other cancer cells." (PMID 34384442, 2021). "Glutathione peroxidase 1 (Gpx1) and peroxiredoxin 2 (Prdx2) belong to the thiol peroxidase family of antioxidants, and have been studied for their antioxidant functions and roles in cancers." (PMID 34679770, 2021). "In contrast, PRDX2 overexpression is related to the development of several malignant tumors, consisting of cancers of the colon, cervix, lung, prostate, liver, and esophagus." (PMID 34490047, 2021). "Previous studies demonstrate that PRDX2 is overexpressed in a variety of cancers and participates in multiple processes of cancer progression." (PMID 34384442, 2021). "In GSE113513 and GSE10950 datasets, bioinformatics analysis revealed that the PRDX2 mRNA level was significantly higher in the cancer tissues compared to the normal tissues." (PMID 34117220, 2021). "The results of these studies suggest that PRDX2 plays a crucial role in the occurrence and development of human cancer." (PMID 33819194, 2021). "Prdx2 expression is elevated in several human cancer cells and tissues and influences diverse cellular processes including survival, proliferation, and apoptosis." (PMID 33182509, 2020). "Together, these studies show that ROS and Prdx2 mediate the cancer growth-limiting activity of Celastrol in mice." (PMID 32929349, 2020). "Prdx2 expression is shown to be elevated in breast 46, lung 47, colorectal 48, and cervical 49 cancers compared to normal tissue." (PMID 32929349, 2020). "This notion is supported by the modest rescue of cancer cell viability from Celastrol upon Prdx2 overexpression, but complete normalization by NAC." (PMID 32929349, 2020). "Previous studies have reported that the levels of PRDX2 were correlated with tumorigenicity, recurrence, and prognosis of patients with different cancers." (PMID 32908916, 2020).